SMAD7 (SMAD family member 7)
Diseases named in the same sentence as SMAD7 in open-access papers (continued):
Sharing a sentence is not in itself a finding about the gene and the disease.
liver cancer (continued). "Taken together, our findings suggest that SMAD7 might exhibit tumor suppressor function, and the lower expression of SMAD7 in liver cancers might predict poor outcome." (PMID 31711043, 2019). "The findings revealed that SMAD7 was down-regulated in liver cancer tissues and cell lines and might play a critical role in the development and progression of liver cancer." (PMID 31711043, 2019). "Taken together, these findings suggested that the overexpression of SMAD7 might prevent liver cancer development in vitro." (PMID 31711043, 2019). "Reppression of Smad7 by miR-195 reinforces TGF-β-mediated growth inhibition in liver cancer." (PMID 31614569, 2019). "Smad7 exhibits a biphasic role in liver cancer development, like that of TGF-β." (PMID 31614569, 2019). "MiR-216a/217-induced EMT targets PTEN and SMAD7 could promote drug resistance and recurrence of liver cancer." (PMID 26164082, 2015). "Besides Smad7, other proteins are also involved in liver cancer by regulating TGF-β receptors." (PMID 31614569, 2019). "The expression of 5 TGFβ-responsive genes (IL11, SERPINE1, SMAD7, SNAI1 and TGFBI) was further validated in other liver cancer cell lines." (PMID 34571856, 2021). "MiR-21-3p-SMAD7/YAP1 axis was identified to better understand the mechanisms of occurrence and development of liver cancer." (PMID 33763375, 2021). "For example, miRNA-216a/217-induced epithelial-mesenchymal transition promotes sorafenib resistance and liver cancer recurrence by targeting PTEN and SMAD7." (PMID 33222692, 2020). "To further reveal the relationship between YAP and SMAD7, we performed the IHC assay by using TMA- containing human liver cancer samples." (PMID 31711043, 2019). "Considering the crucial anti-tumor function of Tan IIA in liver cancer, our study showed the therapeutic importance of Tan IIA and SMAD7 in this malignancy." (PMID 31711043, 2019). "We found that SMAD7 expression was down-regulated in HCC tissues, and YAP proteins were highly expressed in a subset of human liver cancers and negatively correlated with each other." (PMID 31711043, 2019). "Furthermore, we found that SMAD7 and YAP were negatively correlated in liver cancer tissues and cell lines." (PMID 31711043, 2019). "We found that SMAD7 and YAP were negatively correlated in liver cancer tissues and cell lines." (PMID 31711043, 2019). "The expression of SMAD7 and LATS1/2 was down-regulated in liver cancer cells." (PMID 31711043, 2019). "Taken together, these results reveal a close relationship between SMAD7 and YAP in liver cancer." (PMID 31711043, 2019). "Based on these results and our findings from previous several studies focusing on the YAP-mediated mechanism of liver cancer development promotion, we investigated whether YAP and SMAD7 can interact with each other and determined their roles in Tan IIA-induced antitumor activity." (PMID 31711043, 2019).
fibrosis (17 papers, 2011 to 2025). the formation of excess fibrous connective tissue in an organ or tissue in a reparative or reactive process. "The SMAD2, SMAD3, and SMAD4 mRNA expression levels were increased and the SMAD7 mRNA expression level was decreased in the fibrosis control group." (PMID 39055873, 2024). "In the current study, the SMAD2, SMAD3, and SMAD4 mRNA expression levels were determined to be increased, and the SMAD7 mRNA expression level was decreased in the fibrosis control group." (PMID 39055873, 2024). "Other findings showed that miR-21 promoted cardiac fibrosis via the TGF-β/Smad7 signaling pathway after myocardial infarction and via the CADM1/STAT3 pathway in patients with atrial fibrillation." (PMID 35118144, 2021). "In another study, the development of bleomycin-induced fibrosis was partially suppressed by increasing the expression of the Smad7 gene through the introduction of recombinant adenoviral vectors loaded with Smad7 cDNA under cytomegalovirus promoter AdCMV-Smad7." (PMID 36499287, 2022). "It is also possible that up‐regulation of miR‐21 may inhibit cardiac Smad7 expression, resulting in Smad3‐mediated cardiac fibrosis and inflammation as seen in Smad3 WT‐db/db and Smad+/−db/db mice." (PMID 33733577, 2021). "Therefore, we have set the stage for future research focus on a causal link between the observed downregulation of miRNAs and the changes in the expression of TGF-β1, Smad2, Smad3, and Smad7 mRNA, involved in cardiac fibrosis and remodeling." (PMID 28698735, 2017). "Interestingly, we also found that loss of miR-29 may be an additional mechanism through which disruption of Smad7 enhances Ang II-mediated cardiac fibrosis and inflammation." (PMID 23894614, 2013). "Treatment with piperine abolished these effects successfully and resulted in significantly elevated liver expression level of smad-7 with 3.1 folds compared to the fibrosis group and suppression of the expression levels of smad-3 and TGF-β1 by 40.9 and 49.4% compared to the fibrosis group." (PMID 34778375, 2021). "The observation that the lack of Smad7 promoted Ang II-induced cardiac fibrosis and dysfunction identified a critically protective role for Smad7 in Ang II-mediated cardiac remodeling." (PMID 23894614, 2013). "As miR-29b is also negatively regulated by the NF-κB-YY1-miR-29 regulatory circuit, we hypothesized that a loss of renal miR-29b might contribute to the enhanced renal fibrosis and inflammation seen in ANG II infused Smad7 KO mice." (PMID 23301086, 2013).
glioma (17 papers, 2014 to 2023). A benign or malignant brain and spinal cord tumor that arises from glial cells (astrocytes, oligodendrocytes, ependymal cells). "It is also reported that Smad7 inhibits the migratory and invasive activities of glioma, and PTEN inhibits cell proliferation and enhances apoptosis." (PMID 36819921, 2023). "In support of our findings, inhibition of HDAC3 by RGFP966 was shown to promote the differentiation of glioma initiating cells by impairing the TGF-ß signaling pathway mediated by SMAD7." (PMID 35365623, 2022). "Present data indicated that Smad7 was a direct target of miR-15a, and Smad7 was down-regulated in glioma tissues and cells." (PMID 34775378, 2021). "In conclusion, deletion of miR-15a inhibited the activation of EMT signaling via targeting Smad7, thus suppressed the tumorigenesis and tumor growth of glioma." (PMID 34775378, 2021). "Present study showed that deletion of miR-15a inhibited the activation of EMT signaling via targeting Smad7, thus suppressed the tumorigenesis and tumor growth of glioma." (PMID 34775378, 2021). "They demonstrated that downregulated Circ-SMAD7 inhibits cell proliferation, migration, and invasion in glioma cells." (PMID 34858485, 2021). "Luciferase assay indicated that Smad7 was the direct target of miR-15a, and Smad7 was down-regulated in glioma tissues." (PMID 34775378, 2021). "SMAD7 as a Tumor Suppressor: Positive regulation of SMAD7 by LncRNAs: NFκB1 transcriptionally downregulated DGCR5 in glioma cells." (PMID 33511320, 2021). "The silencing of Smad7 reversed the effects of miR-15a inhibitor in EMT pathway and glioma progression, which revealed that miR-15a modulated glioma progression via targeting Smad7." (PMID 34775378, 2021). "In conclusion, lncRNA DGCR5 suppresses the capacity of glioma cells to migrate and invade via miR-21/Smad7, whereas it inhibits the proliferation and enhances the apoptosis of glioma cells through miR-23a/PTEN." (PMID 33085646, 2020). "In conclusion, lncRNA DGCR5 suppresses the capacity of glioma cells to migrate and to invade via miR-21/Smad7, and it inhibits the proliferation and enhances the apoptosis of glioma cells through miR-23a/PTEN." (PMID 33085646, 2020). "Although Smad7 has a dual role in carcinogenesis and cancer cell growth and its functions depend on the type of cancer, in glioma, it has been reported to act as a tumor suppressor." (PMID 33085646, 2020). "In glioma cells, the activation of autophagy by rapamycin treatment increases the expression levels of Smad2/3 and decreases the expression levels of Smad7, leading to TGF-β pathway activation." (PMID 32164764, 2020). "Another study identified SMAD7 as a target of miR-195 in glioma and showed that TGFβ1 promotes miR-195 expression, inhibits SMAD7 expression, and promotes U87 cell proliferation and invasion." (PMID 33085646, 2020). "In fact, miR‐195 expression is known to affect the TGF‐β signaling pathway by targeting SMAD2 and SMAD7 genes in glioma–U87 cell line." (PMID 31581360, 2019). "MTDH promotes miR-130b expression and subsequently downregulates ceRNAs (PTEN, PPP2CA and SMAD7) to induce EMT-like process of glioma cells." (PMID 28107197, 2017). "Moreover, Smad7 is a key regulator of the transforming growth factor β1, which suppresses the migration and invasion capacity of glioma cells." (PMID 35572197, 2022). "In addition, repressed PCNA mRNA and protein expression was observed after circ-SMAD7 was knocked down in the glioma cells, suggesting circ-SMAD7 promotes proliferation and metastasis of glioma via upregulating PCNA." (PMID 34858485, 2021). "Then, we analyzed the expression of Smad7 in glioma tissues." (PMID 34775378, 2021). "MiR-15a-Smad7 axis cannot be proved as the only pathway in glioma development, and Smad7 might only be an intermediary of miR-15a in modulating EMT pathway." (PMID 34775378, 2021).
glioma (continued). "In addition, we identified PTEN as the miR-130b target that functions as the ceRNAs of PPP2CA and SMAD7 and exhibits inhibitory effects on glioma EMT-like process and invasion." (PMID 28107197, 2017). "Moreover, miR-181c modulates the proliferation, migration, and invasion of neuroblastoma cells by targeting Smad7, while miR-181d acts as a tumor suppressor in glioma by targeting K-ras and Bcl-2." (PMID 26473853, 2015). "Also, Zuo and others wanted to examine the role of circ-SMAD7 in glioma progression." (PMID 34858485, 2021). "Our further studies showed that Smad7 might be a potential target of miR-15a in glioma progression." (PMID 34775378, 2021). "Then, we explored whether miR-15a suppressed glioma via modulating Smad7." (PMID 34775378, 2021). "Thus, we investigated whether the DGCR5/miR-21 axis affects Smad7 to act on glioma cell migration and invasion." (PMID 33085646, 2020). "Functional experiments revealed that miR-15a inhibitor inhibited the EMT pathway and the migration and invasion of glioma cells, but the silencing of Smad7 reversed the effects of miR-15a inhibitor in EMT pathway and glioma progression." (PMID 34775378, 2021). "In the present study, we found that miR-15a was up-regulated in glioma tissues, and deletion of miR-15a inhibited the malignancy of glioma cells and EMT pathway via targeting Smad7 both in vitro and in vivo." (PMID 34775378, 2021). "In conclusion, we demonstrate that in glioma cells MTDH acts as a co-activator for NF-kB to upregulate miR-130b expression, which in turn suppresses PTEN, PPP2CA and SMAD7 expression." (PMID 28107197, 2017). "MiR-130b promoted EMT-like change and invasion of glioma cells through targeting multiple EMT-related genes, including PTEN, PPP2CA and SMAD7." (PMID 28107197, 2017). "Furthermore, DGCR5 increased the levels of Smad7 and phosphatase and tensin homolog (PTEN) by sponging miR-21 and miR-23a, respectively, in glioma cells." (PMID 36819921, 2023). "In summary, the DGCR5/miR-21 axis affects glioma cell migration, invasion, and EMT through Smad7." (PMID 33085646, 2020). "In addition, PTEN acted as the competing endogenous RNA (ceRNA) to affect PPP2CA and SMAD7 expression, and inhibited EMT-like change in glioma cells." (PMID 28107197, 2017). "Furthermore, miR-130b promoted glioma EMT-like change by targeting PTEN, PPP2CA and SMAD7, and PTEN acted as the ceRNA for PPP2CA and SMAD7 to inhibit EMT-like change of glioma cells." (PMID 28107197, 2017). "Thus MTDH may regulate the expression of miR-130b-ceRNAs (PTEN/PPP2CA/SMAD7), which in turn regulate EMT-like process and glioma invasion." (PMID 28107197, 2017). "In summary, our study provides data that clearly show that melatonin induces Smad7 expression leading to suppression of TGFβ/Smad-CCL20 activities and EMT in gliomas, indicating that melatonin may be used as a novel therapeutic to treat malignant transformation in gliomas." (PMID 29212174, 2017). "Furthermore, our findings show that melatonin deregulates Smad7 expression to suppress TGFβ/Smad-mediated increase in CCL20 transcript levels and CCL20-induced EMT occurrence, suggesting potential anti-EMT therapeutic strategy of melatonin to overcome malignant transformation in gliomas." (PMID 29212174, 2017). "Furthermore, our findings show that melatonin deregulates Smad7 expression to suppress TGFβ/Smad-mediated increase in CCL20 transcript levels and CCL20-induced EMT occurrence, suggesting a potential anti-EMT therapeutic role for melatonin in malignant transformation in gliomas." (PMID 29212174, 2017).
prostate carcinoma (17 papers, 2008 to 2023). A carcinoma that arises from epithelial cells of the prostate gland. "For example, SMAD7 activates the TAK1-p38 MAPK pathway in human prostate cancer cells, whereas Smad6 inhibits TGF-β1-induced activation of this pathway." (PMID 37272627, 2023). "The ability of Smad7 to act as a transcription factor has been previously shown in prostatic cancer cells, where Smad7 can bind the regulatory regions and enhance the expression of c-Jun and Histone deacetylase 6, two tumor-promoting genes." (PMID 36291778, 2022). "Our identification of HDAC6 as a downstream target gene of Smad7 in response to TGF-β is therefore of clinical importance for patients with prostate cancer, as HDAC6-inhibitors are currently investigated for their effects on cancer cells in clinical trials." (PMID 32888405, 2020). "The knowledge that Smad7 can activate transcription of proinvasive genes leading to prostate cancer progression provides clinically relevant information." (PMID 32888405, 2020). "Smad7 expression has been reported to be localized in basal epithelial cells in the prostate gland in a murine prostate cancer model, in line with our current observations." (PMID 32888405, 2020). "From these data, we conclude that the expression of HDAC6, Smad7, and c-Jun correlates with poor prognosis for patients with prostate cancer." (PMID 32888405, 2020). "The expression of HDAC6, Smad7, and c-Jun was examined by immunohistochemistry in tissue sections from patients with prostate cancer and in tissue sections from normal prostate gland." (PMID 32888405, 2020). "High Smad7 expression was reported to be correlated with the clinical prognosis of patients with colorectal, pancreatic, liver, and prostate cancer." (PMID 30498395, 2018). "Initial studies showed that Smad7 was expressed in rat prostate cancer cells undergoing apoptosis and ectopic Smad7 expression induced apoptosis of PC-3U human prostate cancer cells." (PMID 24317436, 2013). "We identified previously that c-Jun, a member of AP-1 transcription factors, is activated by TGF-β in a TRAF6-dependent manner leading to invasion of prostate cancer cells and that the Smad7-APC complex links TβRI to the microtubule system to promote migratory responses of prostate cancer cells." (PMID 32888405, 2020). "In the current study, we report that Smad7 promotes expression of HDAC6 in prostate cancer cells." (PMID 32888405, 2020). "Interestingly, while it has been reported that expression of Smad7 is needed for TGFβ-mediated apoptosis in normal epithelial cells (HaCaT) and prostatic carcinoma cells (PC-3U), in human tissues Smad7 activity is correlated to tissue specificity." (PMID 25501935, 2014). "Evidence linking Smad7 and prostate cancer comes from the work of Landstrom’s group." (PMID 24317436, 2013). "SMAD7 enhanced TGF-β induction of c-Jun and HDAC6 and contributed to tumor aggressiveness in prostate cancer cells." (PMID 35912252, 2022). "Smad7 is also directly involved in gene transcription in cancer cells, as the Smad7 protein can bind to specific regions in the promoter of c-Jun and histone deacetylase 6 (HDAC6) in prostate cancer cells, promoting migration and invasion." (PMID 35625561, 2022). "Here we report an additional function of Smad7, i.e., to enhance TGF-β induction of c-Jun and HDAC6 via binding to their regulatory regions, promoting migration and invasion of prostate cancer cells." (PMID 32888405, 2020). "A correlation between the mRNA expression of Smad7 and HDAC6, Smad7 and c-Jun, and c-Jun and HDAC6 was found in public databases from analyses of prostate cancer tissues." (PMID 32888405, 2020). "We found a positive correlation between Smad7 and c-Jun mRNA, Smad7 and HDAC6 mRNA, and c-Jun and HDAC6 mRNA in tumor material from patients with prostate cancer." (PMID 32888405, 2020). "High expression of Smad7, HDAC6, and c-Jun correlated with poor prognosis for patients with prostate cancer." (PMID 32888405, 2020).
prostate carcinoma (continued). "In summary, we have described a novel role for Smad7 as a transcriptional regulator of c-Jun and HDAC6 in prostate cancer cells, promoting migration and invasion." (PMID 32888405, 2020). "For instance, a mouse study in which the growth and invasion of prostate cancer cells, with or without knockdown of Smad7, HDAC6, or c-Jun, is missing." (PMID 32888405, 2020). "The TGF-β- and Smad7-induced increases of c-Jun and HDAC6 promote invasion of prostate cancer cells, making it relevant to investigate expression of Smad7, c-Jun, and HDAC6 in clinical tissue samples of patients with prostate cancer as potential biomarkers and drug targets." (PMID 32888405, 2020). "Moreover, a high co-expression of Smad7 and HDAC6, and c-Jun and HDAC6, was observed in prostate cancer tissues, which correlated with poor prognosis." (PMID 32888405, 2020). "Moreover, a high co-expression of Smad7 and HDAC6, and c-Jun and HDAC6 was also observed in prostate cancer tissues, which correlated with poor prognosis." (PMID 32888405, 2020). "Additionally, Smad7 was found to act as a scaffold protein to facilitate TGF-β-induced activation of p38 and subsequent apoptosis in prostate cancer cells." (PMID 30498395, 2018). "In breast and prostate cancer cells, halofuginone increased Smad7 mRNA; however knockdown of Smad7 did not prevent halofuginone inhibition of TGF-β-regulated genes." (PMID 29156807, 2017).